SPACA3 (sperm acrosome associated 3)
Description:
Sperm surface membrane protein that may be involved in sperm-egg plasma membrane adhesion and fusion during fertilization. It could be a potential receptor for the egg oligosaccharide residue N-acetylglucosamine, which is present in the extracellular matrix over the egg plasma membrane. The processed form has no detectable bacteriolytic activity in vitro.
Synonyms: CT54; LYC3; LYZL3; SLLP1; ALLP17; LYZC
Tractability: Antibody: UniProt places it where antibodies can reach, with high confidence; UniProt predicts a signal peptide or a membrane-spanning region; its Gene Ontology location is reachable by antibodies, with medium confidence.
Gene: Protein-coding gene on chromosome 17 (32,970,376 to 32,997,877, forward strand). Ensembl gene ENSG00000141316.
Subcellular location: Cytoplasmic vesicle, secretory vesicle, acrosome membrane (Isoform 1); Secreted (Isoform 2)
Subcellular location (Human Protein Atlas): Acrosome; Predicted to be secreted
Gene Ontology:
Molecular function: lysozyme activity; protein binding
Biological process: fusion of sperm to egg plasma membrane involved in single fertilization; monocyte activation; positive regulation of macrophage activation; positive regulation of phagocytosis
Cellular component: acrosomal matrix; acrosomal membrane; secretory granule; acrosomal vesicle; sperm flagellum; extracellular region
Genetic constraint (gnomAD): Loss-of-function variants: 21 observed, 25.16 expected, observed/expected ratio (o/e) 0.83, 90% interval 0.59 to 1.2. The upper end of that interval is the gene's LOEUF score, 1.2, which puts it in group 5 of 6, group 1 being the genes least tolerant of losing a copy. Missense variants: 278 observed, 281.62 expected, observed/expected ratio (o/e) 0.99, 90% interval 0.89 to 1.09. Synonymous variants: 115 observed, 110.71 expected, observed/expected ratio (o/e) 1.04, 90% interval 0.89 to 1.21.
Homologues: Orthologues: chimpanzee SPACA3 (98% identical), guinea pig SPACA3 (67% identical), pig SPACA3 (59% identical), dog SPACA3 (59% identical), rabbit SPACA3 (58% identical), mouse Spaca3 (56% identical), rat Spaca3 (56% identical), macaque SPACA3 (44% identical), Drosophila melanogaster CG30062 (24% identical), Drosophila melanogaster CG7798 (23% identical), Drosophila melanogaster CG11159 (21% identical), Drosophila melanogaster CG16756 (21% identical), and 7 more. Paralogues in human: LYZ (31% identical), SPACA5 (31% identical), SPACA5B (31% identical), LYZL1 (30% identical), LYZL4 (29% identical), LYZL6 (29% identical), LYZL2 (29% identical), LALBA (22% identical).
Diseases named in the same sentence as SPACA3 in open-access papers:
SPACA3 is named in the same sentence as 12 diseases in open-access papers, as found by Europe PMC text mining. Sharing a sentence is not in itself a finding about the gene and the disease.
SPACA3 shares sentences with these, for which no sentence is quoted: cancer (3 papers); bacterial infection (1); COVID-19 (1); hematologic malignancies (1); infection (1); infertile (1); melanoma (1); multiple myeloma (1); myeloma (1); osteosarcoma (1); pancreatic adenocarcinoma (1); tumor (1).